LINC00311 (long independently transcribed non-coding RNA 311)
Synonyms: NCRNA00311; TMEM148; MGC22001
Gene: Long non-coding RNA gene on chromosome 16 (85,282,958 to 85,285,963, forward strand). Ensembl gene ENSG00000179219.
Diseases named in the same sentence as LINC00311 in open-access papers:
LINC00311 is named in the same sentence as 3 diseases in open-access papers, as found by Europe PMC text mining. Sharing a sentence is not in itself a finding about the gene and the disease. The quoted sentences say what the papers report.
ankylosing spondylitis (2 papers, 2019 to 2020). An autoimmune chronic inflammatory disorder characterized by inflammation in the vertebral joints of the spine and sacroiliac joints. "LncRNA LINC00311 participates in osteoporosis, which shows inverse pathological changes to ankylosing spondylitis (AS), indicating that LINC00311 is also involved in AS." (PMID 31170957, 2019).
LINC00311 also shares sentences with these, for which no sentence is quoted: breast carcinoma (1 paper); osteoporosis (1).